ERBB2 (erb-b2 receptor tyrosine kinase 2)
Diseases named in the same sentence as ERBB2 in open-access papers (continued):
Sharing a sentence is not in itself a finding about the gene and the disease.
breast cancer (continued). "Indeed, one of these therapies, herceptin (trastuzumab), a monoclonal antibody against the extracellular domain of ErbB2, has shown significant clinical benefit for patients with ErbB2-positive breast cancers." (PMID 20840765, 2010). "Trastuzumab, the only humanised anti-ErbB2 antibody currently used in breast cancer, has proven to be effective; however, a relevant problem for clinical practice is that a high fraction of breast cancer patients shows primary or acquired resistance to trastuzumab treatment." (PMID 20051960, 2010). "In addition, we previously reported that the phosphorylation on tyrosine-15 of Cdc2 by ErbB2 in breast cancer cells resulting a delayed M phase entry and leading to an increased Taxol resistance." (PMID 20144215, 2010). "In summary, data on the prevalence of ErbB2-positive breast cancer in Asia are limited." (PMID 20715159, 2010). "Additionally, our data identified AS transcript candidates whose expression was influenced by ERBB2-mediated expression and can be tested as molecular markers for breast cancer." (PMID 21210970, 2010). "The phenotypic analysis of tumor specimens demonstrated that hTid and ErbB-2 expression are inversely correlated in breast cancer either primary (p < 0.0001) or metastatic (p < 0.023), in primary non-breast tumors (p < 0,007) and in breast tumors generated in HER-2/neu transgenic mice." (PMID 20565727, 2010). "The gene expression profile of the Cowden tumors shows considerable overlap with that of a breast cancer subgroup known as molecular apocrine breast carcinoma, which is suspected to have increased androgenic signaling and shows frequent ERBB2 amplification in sporadic tumors." (PMID 20712882, 2010). "We believe that our conclusions regarding the prevalence of ErbB2-positive breast cancer and ErbB2 assessment methods in Asia are strengthened by the use of data from 22 studies involving more than 14,000 patients in 7 Asian countries that vary in ethnicity, size, and economic status." (PMID 20715159, 2010). "Gene amplification of ERBB2 is found in 20–30% of breast cancer patients." (PMID 20010942, 2010). "Consistent with our current report, mammary tumor cells derived from both transgenic mice and cell lines with high expression of Cks1 failed to reveal a decrease of p27Kip1; in fact p27Kip1 levels were slightly higher in mammary tumors initiated by erbB2, PyMT and MNU." (PMID 20930946, 2010). "ErbB2 (Her2, neu) overexpression is observed in 20–30% human breast cancer." (PMID 20174572, 2010). "We suggest that the TNFAIP1/POLDIP2 CSAGA represents a clinically significant transcriptional structural-functional gene module associated with amplification of the genomic region on 17q11.2 and correlated with expression ERBB2 amplicon core genes in breast cancer." (PMID 20158880, 2010). "In addition, the genes TCAP, PSMD3, GRB7, and ERBB2 from the ERBB2 group are derived from the same well known breast cancer amplicon." (PMID 20158879, 2010). "Data on the prevalence of ErbB2-positive breast cancer in Asia are limited." (PMID 20715159, 2010). "This approach efficiently recognized 15 differentially DNA-methylated loci, which were further validated through pyrosequencing in an independent cohort encompassing 47 basal-like, 44 ERBB2+ overexpressing, 48 luminal A, and 48 luminal B paired breast cancer/adjacent tissues." (PMID 20920229, 2010). "Whether the prevalence of ErbB2-positive breast cancer differs between Asian and Western countries requires clarification." (PMID 20715159, 2010). "Fourth, PTEN-deficient/Erbb2KI transgenic mice show accelerated mammary tumor onset associated with elevated ERBB2 protein levels that are not caused by ERBB2 amplification." (PMID 20712882, 2010). "ErbB-2 is a well-known poor prognostic factor in breast cancer." (PMID 20858260, 2010).
breast cancer (continued). "We subsequently performed substantial technical and biologic validation by pyrosequencing, investigating the top qualifying 19 CpG regions in independent cohorts encompassing 47 basal-like, 44 ERBB2+ overexpressing, 48 luminal A, and 48 luminal B paired breast cancer/adjacent tissues." (PMID 20920229, 2010). "As an essential step to gain knowledge about function of KLF6 in breast tumors, the expression pattern and sub-cellular distribution of KLF6 protein was analyzed in samples of human breast cancer along with the expression of ERBB2 as a tumor aggressiveness marker." (PMID 20126619, 2010). "Breast cancer represents a heterogeneous disease in oncology and the ERBB2 status has become a routine prognostic and predictive factor in standard measurements in the management of patients together with Estrogen Receptor alpha, which are expressed in up to 70% of all breast cancers." (PMID 20126619, 2010). "While the contribution of the IGF-IR to ErbB2 signaling and resistance to ErbB2-directed therapies in breast cancer has been studied in several systems, the reciprocal interaction remains almost completely unknown." (PMID 20825649, 2010). "The current survey indicated that the prevalence in Asia may be similar to that in Western countries; thus, up to 1 in 4 Asian patients with breast cancer potentially could benefit from ErbB2-targeted treatment." (PMID 20715159, 2010). "It has been previously postulated that targeting multiple signaling pathways such as IGF-IR and ErbB2 may be beneficial to the treatment of breast cancer." (PMID 20825649, 2010). "For example, Scott and colleagues reported that miR-125a and miR-125b could reduce invasion and migration capacity of SKBR3 breast cancer cells through targeting ERBB2 and ERBB3 genes." (PMID 20932331, 2010). "Similar to ERBB2 amplification in breast cancer, high-level CCNE1 amplification may therefore have predominant clinical utility in identifying patients most likely to have a poor response to standard treatment." (PMID 21103391, 2010). "Decorin has been shown to inhibit the growth of both primary breast cancer xenografts and metastatic spread by inactivating the oncogenic ErbB2 protein in breast carcinoma cells and downregulating members of the ERb tyrosine kinase family, leading to growth inhibition." (PMID 20398359, 2010). "In addition, SRCs have been shown to interact with human epidermal growth factor receptor 2 (HER2/erbB2), and overexpression of HER2 and SRC-3 are both associated with a worse prognosis in cases of human breast cancer." (PMID 20675265, 2010). "Furthermore, tyrosine kinase membrane receptors are also mutated or activated (ie: ErbB2, EGFR) contributing to AKT deregulation in mammary tumors." (PMID 20174572, 2010). "A higher prevalence of ErbB2-positivity may be 1 of several factors contributing to the lower survival rate of Asian breast cancer patients." (PMID 20715159, 2010). "THC also decreased cell proliferation of two different ErbB2-overexpressing breast cancer cell lines of human origin, suggesting that human ErbB2-positive breast tumor cells may be sensitive to cannabinoid antitumoral action as well." (PMID 20649976, 2010). "RM11A+Dox/ErbB2 cells produced palpable mammary tumors approximately 22 days post injection." (PMID 20825649, 2010). "Indeed, AGR2, LCP1 and S100P overexpression have been previously correlated with breast cancer progression, and we now link the aberrant expression of these genes with ErbB2 expression." (PMID 20840765, 2010). "ERBB2, or HER-2/neu, is an oncogene that is over-expressed in 20-30% of human breast carcinomas and is associated with poor prognosis, independent of the lymph node status." (PMID 21210970, 2010). "Among these, inhibiting Ku activity might be evaluated as an adjuvant for ERBB2 targeted therapy in breast cancer." (PMID 19906305, 2009). "PPARγ expression is also higher in ERBB2-positive breast cancer cells." (PMID 19298655, 2009).
breast cancer (continued). "This study shows that the adipogenic transcription factor PPARγ is critical for ERBB2-positive breast cancer cells to convert the high levels of fatty acids that they produce into triglycerides, allowing them to avert the cell death that results from lipotoxicity." (PMID 19298655, 2009). "Trastuzumab is administrated to ERBB2-overexpressing breast cancer patients." (PMID 19118495, 2009). "Moreover, similar data on Herceptin-mediated regulation of FA turnover was observed in T47D cells, a breast cancer cell line that express intermediate endogenous ErbB2." (PMID 19190626, 2009). "In particular, adding trastuzumab, a recombinant humanized monoclonal antibody directed against the ectodomain of the receptor tyrosine kinase ERBB2, to regimens containing existing chemotherapeutic agents has significantly improved clinical outcomes for breast cancer patients." (PMID 19118495, 2009). "Although several growth factor receptors, such as epidermal growth factor receptor, ErbB2 and FGFR1, have been studied and implicated in breast cancer, we are only beginning to understand how these growth factor pathways interact with other autocrine or paracrine factors to promote tumourigenesis." (PMID 19393083, 2009). "Similarly, cdk4−/− mutant mice show normal proliferation in many tissues, but are resistant to ErbB-2-driven breast cancers." (PMID 19214224, 2009). "Besides being a poor prognosis marker, ERBB2 amplification is a predictive marker for targeted therapy with the monoclonal antibody trastuzumab in breast cancer patients with metastatic disease." (PMID 19156142, 2009). "Recentstudies have demonstrated that it may be advantageous to inhibit ErbB1 andErbB2 simultaneously in those patients overexpressing the ErbB2/HER-2/neu gene,which constitutes approximately 25% of all cases of primary breast cancer." (PMID 19390622, 2009). "In correlation with this hypothesis, recent studies show that the expression of metalloprotease MMP9 from the tumour surrounding stroma, unlike its expression in tumour cell cytoplasm, correlates with unfavourable prognosis in ERBB2 positive breast cancer." (PMID 19183447, 2009). "We recently showed that ERBB2-positive breast cancer cells produce significantly high amounts of fats, because of overexpression of the peroxisome proliferator-activated receptor (PPAR)γ-binding protein and the nuclear receptor NR1D1 (nuclear receptor subfamily 1, group D, member 1; Rev-erbα)." (PMID 19298655, 2009). "Most human BRCA1-mutated breast cancers are ‘triple-negative’ tumours that do not express ER, PR and ERBB2." (PMID 19904273, 2009). "In agreement with the original findings by Lynch and Daly (2002), a recent study comparing murine breast cancers driven by an ErbB2 transgene alone or in combination with an constitutively activated AKT transgene showed that the phosphorylation of Gab2 at Y452 was dramatically reduced in the latter." (PMID 19737390, 2009). "In conclusion, our data show that preferential relapse sites for triple negative breast cancers may be quite distinct from that for HR+/ERBB2- and ERBB2+ counterparts in Chinese breast cancer patients." (PMID 19778431, 2009). "It described the amplification of the ERBB2 RTK gene in a good proportion of breast cancers." (PMID 19226453, 2009). "A correlation between the tyrosine phosphorylation status of Gab1 and the progression of ErbB2-transgene driven murine mammary tumours has also been reported, indicating that Gab1 needs to be considered as an important downstream effector of this oncogenic RTK as well." (PMID 19737390, 2009).
breast cancer (continued). "To determine whether βGBP could overcome the strength of endogenous mitogenic signalling in aggressive cancers we examined BT474 and SKBR3 breast cancer cells that express high levels of ErbB2." (PMID 19133120, 2009). "Interrupting the ERBB2-ERBB3 heterodimer using lapatinib (GW572016, GlaxoSmithKline), a potent small-molecule inhibitor of EGFR and ERBB2 tyrosine kinases, leads to proteasomal degradation of BIRC5 and induces apoptosis both in breast cancer cell lines overexpressing ERBB2 and in primary tumors." (PMID 19007432, 2008). "Moreover, YY1 enhances AP-2α, AP-2β, and AP-2γ transcriptional activity on the ERBB2 promoter in breast cancer cells." (PMID 18218085, 2008). "Taken together, our results suggest that bispecific targeting of ErbB2 and ErbB3 with ALM may be efficacious in vivo against breast cancers with a wider range of ErbB2 expression than those amenable to the trastuzumab therapy available at present." (PMID 18841159, 2008). "To find out whether AP-2 factors do contribute functionally to ERBB2 overexpression in vivo, we measured ERBB2 mRNA levels in breast cancer cells in which the expressions of AP-2α and AP-2γ were downregulated by siRNAs." (PMID 18218085, 2008). "However, the effect of combination therapy and the therapeutic effect for selected patients, such as those with tumors expressing a particular hormone receptor, ERBB2 (HER2) status or those in earlier stages of breast cancer, remain to be determined." (PMID 19007432, 2008). "Similarly, deletion of one or both alleles of phosphatase and tensin homolog (PTEN), a negative regulator of Akt signalling, accelerates tumour induction in another ErbB2 mouse mammary tumour model." (PMID 18700973, 2008). "In this report, we demonstrate that the novel small molecule compound NVP-AUY922 potently inhibits HSP90 in vitro, has good pharmaceutical and pharmacological properties, and exhibits potent antitumor activity at tolerated doses in an ER- and ERBB2-positive human breast cancer model." (PMID 18430202, 2008). "Thus, downregulation of ERBB2 by means of acceleration of the UPS is of crucial importance to breast cancer treatment." (PMID 19007432, 2008). "Indeed, we have previously shown that YY1 is able to enhance AP-2α, AP-2β, and AP-2γ transcriptional activity in vitro and that it is recruited via AP-2 to the ERBB2 endogenous promoter in a breast cancer cell line." (PMID 18218085, 2008). "Interestingly, however, the proteasome inhibitor bortezomib has an additive or synergistic effect with trastuzumab in the induction of apoptosis in ERBB2-positive breast cancer cell lines." (PMID 19007432, 2008). "Moreover, we showed that at least two mechanisms can lead to pathological ERBB2 overexpression in breast cancer: ERBB2 gene amplification and increased transcription through high levels of transcriptional activators, such as AP-2α and YY1." (PMID 18218085, 2008). "The overexpression of Pin1 in a majority of Her2-overexpressing breast cancer may contribute to maintain erbB2 levels." (PMID 19077306, 2008). "Finally, AP-2 transcription factors have been shown to be highly expressed in breast cancer cell lines overexpressing ERBB2." (PMID 18218085, 2008). "FISH demonstrated ERBB2 gene amplification in 11 cases of breast cancer." (PMID 18218085, 2008). "The ErbB2 and ErbB3 receptors are frequently co-expressed in human breast cancer, but potentially more indicative of the importance of ErbB2/ErbB3 heterodimers in driving breast cancer progression is the link between escape from ErbB2-targeted therapies and a gain in ErbB3 activity or expression." (PMID 18841159, 2008). "On the basis of multiple lines of evidence, we hypothesised that the ErbB2/ErbB3 heterodimer would be a valuable target for the development of a bsAb for the treatment of breast cancer." (PMID 18841159, 2008). "Moreover, ERBB2 gene overexpression is able to transform cells in culture and to induce mammary tumors in transgenic mice." (PMID 18218085, 2008).
breast cancer (continued). "The importance of ErbB3 expression in breast cancer has been recently highlighted by the demonstration that continued oncogenic signalling through ErbB3 in human breast cancer cell lines results in the failure of gefitinib to completely inhibit the kinase activity of ErbB2." (PMID 18283314, 2008). "The ErbB2/ErbB3 receptor pair forms the most potent mitogenic receptor complex in vitro and is key to the proliferation of human breast cancer cells." (PMID 18283314, 2008). "Altogether, our data indicate that ERBB2 gene amplification or increased levels of transcription factors may lead to a pathologically high level of ERBB2 transcript and protein in breast cancer." (PMID 18218085, 2008). "Indeed, trastuzumab has switched ERBB2-positive breast cancer from being a subset with the worst prognosis to one that is curable with existing therapy." (PMID 19007432, 2008). "Moreover, we demonstrated that ERBB2 endogenous expression is inhibited by the downregulation of both AP-2α and AP-2γ in a breast cancer cell line." (PMID 18218085, 2008). "This gives rise to the hypothesis that expression of activated Akt could compensate for the expression of ErbB3 in ErbB2-induced mammary tumours." (PMID 18700973, 2008). "Also, it seems that the prognosis and response to therapy varies considerably within the spectrum of ERBB2-amplified breast carcinomas (BC), indicating that they are biologically heterogeneous." (PMID 18702822, 2008). "The ErbB2 gene is amplified in 20–30% of breast carcinomas contributing to more aggressive disease." (PMID 18283314, 2008). "Indeed, it has been reported that basal levels of erbB2/erbB3 heterodimers are greatly reduced following treatment of BT-474 breast cancer cells with gefitinib, resulting in a substantial blunting of response to HRGβ1 treatment." (PMID 17686159, 2007). "Moreover, Grb7 is co-expressed with ErbB3 and ErbB4, which are known to heterodimerise with ErbB2, in a subgroup of human breast cancer cell lines." (PMID 17426702, 2007). "The breast cancer death rates for the highly proliferating luminal, the basal-like and the ERBB2+ groups are about six times higher than for the luminal A group, while the breast cancer death rate for the normal-like group is almost three times that of the luminal A group." (PMID 17504517, 2007). "Similar findings were observed in ErbB2-induced mammary tumours from transgenic mice." (PMID 17426702, 2007). "In the same study, however, we also demonstrated that the specific gene-expression profile of breast tumours from patients with IBC is not only attributable to the preferential segregation of these breast tumours in the basal-like or ErbB2-overexpressing breast cancer subtypes." (PMID 17848951, 2007). "Furthermore, this combination treatment was shown to increase erbB3 activity in erbB2-overexpressing breast cancer cells." (PMID 17686159, 2007). "In addition, the topoisomerase II α gene, TOP2 α, is located at chromosome band 17q12-q21, close to the ErbB-2 oncogene (HER-2/neu), which is the most commonly amplified oncogene in breast cancer." (PMID 17551498, 2007). "A variety of genes involved in breast cancer biology have been studied and proposed as prognostic or predictive biomarkers, but only a few of them, such as hormone receptors and ERBB2, are used today to classify breast cancer patients and to make treatment decisions in the clinical routine." (PMID 17535433, 2007). "ERBB2/Her2 is frequently over-expressed in breast cancer, and is transforming simply by being over-expressed, so this line models clinically relevant features of breast cancer." (PMID 17233903, 2007).